MCL1 (MCL1 apoptosis regulator, BCL2 family member)
Diseases named in the same sentence as MCL1 in open-access papers (continued):
Sharing a sentence is not in itself a finding about the gene and the disease.
cancer (continued). "Finally, to extend our observations beyond HCT116 and HeLa cells, we made use of the Broad Institute’s Cancer Dependency Map51 to assess the correlation between MCL1 expression and chemosensitivity across hundreds of cancer cell lines and dozens of lineages." (PMID 40909578, 2025). "MCL1 and HAX1 are key regulators of apoptotic resistance, and their overexpression is associated with poor prognosis and therapeutic resistance in various cancers." (PMID 41154579, 2025). "MCL-1 may be a key molecule leading to drug resistance in patients, and it is involved in regulating apoptosis and chemoresistance in cancers." (PMID 38468814, 2024). "Similarly, MCL1 upregulation has been observed to protect cancer cells from undergoing ferroptosis, characterized by lipid peroxidation." (PMID 38485916, 2024). "Moreover, this activation of STAT3 enhances the expression of anti-apoptotic proteins, such as Bcl-2, Bcl-XL, and Mcl-1, in cancer cells, thereby increasing resistance to cell death." (PMID 38510850, 2024). "Therefore, blocking the STAT3-Mcl-1 pathway in cancer has been demonstrated to reduce Mcl-1 levels, which in turn promotes programmed cell death in cancer cells." (PMID 39411073, 2024). "In addition, differential regulation of another anti-apoptotic BCL-2 family member MCL-1, which plays a critical role in the regulation of apoptosis, has been reported in human primary and drug-resistant cancer cells, including CLL." (PMID 39061962, 2024). "Targeting the BCL-2 protein family provides a promising area of investigation for the treatment of paediatric nervous system tumours, as the anti-apoptotic BCL-2 family members BCL-2, BCL-XL, and MCL-1 are frequently upregulated in cancer cells, including MB and NB." (PMID 38942989, 2024). "Of note, MCL1 is an essential anti-apoptotic gene involved in c-MYC-driven cancer development, and the synergy of MCL1 with c-MYC overexpression could suppress c-MYC-driven apoptosis and trigger liver tumor development." (PMID 39062197, 2024). "We previously showed that Mcl-1 may play an important role in protecting cancer cells from IMQ-induced cell death." (PMID 39272918, 2024). "This makes MCL1 an attractive therapeutic target for cancer therapy." (PMID 39802137, 2024). "Herein, therapeutic targeting MCL-1 is an attractive focus for cancer treatment." (PMID 38706892, 2024). "Mcl-1 is a promising therapeutic target in the treatment of cancer." (PMID 38928234, 2024). "It is possible that Mcl-1 may increase Nrf2 activation to protect cancer cells from IMQ-induced oxidative stress." (PMID 39272918, 2024). "Potential targets associated with cancer were HMG-CoA reductase, Bcl-2, Mcl-1, and VEGFR-2." (PMID 39769118, 2024). "Moreover, several studies reported ERK inhibitors when combined with MCL1 inhibitors can enhance cancer cell killing." (PMID 39802137, 2024). "Similarly, in colorectal KRAS-mutant cancer cells, trametinib downregulates Mcl-1 levels in a ubiquitin–proteasome-dependent manner through E3 ligase activation." (PMID 38643157, 2024). "As a result of these features, MCL1 is an attractive target for cancer therapy." (PMID 39179926, 2024). "Finally, molecular docking studies were performed using cancer-associated proteins as targets, including HMG-coA reductase, Bcl-2, Mcl-1, and VEGFR-2." (PMID 39769118, 2024). "Recent studies have suggested that VEGF stimulates the overexpression of myeloid cell leukaemia 1 (MCL-1) in cancers and malignancies, which is essential for cancer cell survival and development due to the balance disruption between anti- and proapoptotic proteins." (PMID 38213742, 2024).
cancer (continued). "Consequently, cancer cells with elevated MCL1 expression are endowed with a survival advantage, counteracting the cytotoxic effects of therapies and leading to therapeutic resistance." (PMID 38485916, 2024). "In addition, a morphological analysis of the lymph nodes obtained from Balb-c mice with NHL and a molecular docking study using proteins related with cancer, namely, Bcl-2, Mcl-1 and VEGFR-2, were performed." (PMID 38731446, 2024). "In recent years, the search for molecules that bind to the BH3 domain on Bcl-2 and Mcl-1 has been proposed, as it could be promising for the therapy of cancers and some types of NHL with the overexpression of these proteins." (PMID 38731446, 2024). "Remarkably, while efficiently killing many cancer cells, MCL-1 inhibition is well tolerated by mice, indicating that non-transformed cells are naturally resistant to MCL-1 inhibition; cardiac damage of MCL-1 inhibitors is probably due to specific blockade of non-anti-apoptotic effects of MCL-1." (PMID 39285161, 2024). "This could partly explain the differences in apoptosis induction between the two treatments since the lower effectiveness of selumetinib+capivasertib could be due to the adaptation of cancer cells to therapy through the MCL-1 antiapoptotic protein." (PMID 38318136, 2024). "Some cancers have elevated levels of MCL1 protein and are resistant to therapy." (PMID 39802137, 2024). "This points to MCL1 as a possible target in PB; the inhibition of MCL1 in patients with MCL1-amplified cancer could be beneficial." (PMID 38256213, 2024). "However, Mcl-1-overexpressing cancer cells contained more abundant tubular mitochondria than fragmented mitochondria." (PMID 39272918, 2024). "Importantly, the main anti-apoptotic proteins BCL-2, B-cell lymphoma-extra large (BCL-XL) and myeloid cell leukaemia 1 (MCL-1) are often upregulated across many adult and paediatric cancer types." (PMID 38942989, 2024). "Among these, AZD-4573 is a highly selective CDK9 inhibitor that induces cancer cell apoptosis and cell death via MCL-1 depletion, thus showing promising preclinical in vivo efficacy, both as a monotherapy and in combination with Venetoclax, in hematologic cancer models." (PMID 38172923, 2024). "Yet the individual influences of BCL-xL, MCL-1, and BCL-2 on the sensitivity of TNBC cells to chemotherapy, and their regulation by cancer-associated fibroblasts (CAFs), major components of the tumor stroma and key contributors to therapy resistance remain to be delineated." (PMID 38898061, 2024). "In contrast, overexpressed Mcl-1 in cancer cells protects these cells from IMQ-induced apoptosis." (PMID 39272918, 2024). "The depletion of KIF18A showed a trend toward increased cyclin B1 (G2M marker) and cl-PARP (apoptosis marker) protein levels as well as decreased MCL-1 (a pro-survival marker) protein levels in those cancer cell lines sensitive to KIF18A KD in our cell growth assay." (PMID 38151625, 2024). "Also, a morphological analysis of the lymph nodes and a molecular docking study using three proteins related with cancer as targets, namely, Bcl-2, Mcl-1 and VEGFR-2, were performed." (PMID 38731446, 2024). "However, the inhibition of either BCL-xL or MCL-1 alone is insufficient to initiate a massive apoptotic response in this studied cancer line." (PMID 38898061, 2024). "MCL-1 is an essential gene for cancer survival and tumorigenesis." (PMID 39540618, 2024). "Thus, our data suggest that PRKCSH contributes to tumor resistance against various cancer therapeutics as well as the TNFSF response via Mcl-1 mRNA transcription regulation." (PMID 38200153, 2024). "Investigating the roles of Mcl-1 in mitochondria may lead to its designation as a potential target for IMQ-related cancer therapy." (PMID 39272918, 2024).
cancer (continued). "MCL1 is a pro-survival (antiapoptotic) protein commonly expressed in hematological tumors and plays an important role in their biology, either through dysregulation or due to its intrinsic importance to the cells of origin of malignant tumors." (PMID 38225547, 2024). "Apoptosis, which is a key hallmarkof cancer, is associated with the deregulation of the balance betweenproapoptotic proteins and antiapoptotic proteins such as BCL-2,BCL-xl,BFL-1, BCL-w, BRAG-16, and MCL-1." (PMID 38882173, 2024). "However, its non-apoptotic roles await in vivo characterisation to develop successful Mcl-1 inhibitors for cancer therapy." (PMID 37663116, 2023). "Furthermore, enhanced CDK9-mediated transcription elongation increases the expression of prosurvival and antiapoptotic proteins, such as c-Myc, Mcl-1, and survivin, thereby contributing to the proproliferative and antiapoptotic phenotype of cancer cells." (PMID 35088192, 2023). "A 2017 study reported that CLK inhibition could modulate the alternative splicing of Mcl-1, an anti-apoptotic protein, and promote cancer cell death, suggesting a potential therapeutic approach for cancer treatment." (PMID 37568654, 2023). "Once completed, these studies may shed some invaluable light on the utility of MCL-1 inhibitors for cancer treatment and might encourage clinical trials against solid cancers." (PMID 36672454, 2023). "Downregulation of MCL1 markedly enhances apoptotic cancer cell death." (PMID 36672167, 2023). "Thus, MCL1 not only suppresses apoptosis in cancer cells, but also regulates β-oxidation in response to stress." (PMID 37842232, 2023). "For example, antiapoptotic proteins, such as BCL-2, BCL2L2 and MCL1, can block autophagy in cancer." (PMID 36768482, 2023). "In addition, XIAP and MCL1 are antiapoptotic proteins that are overexpressed in several types of cancers and whose expression is regulated by MNK1." (PMID 37111758, 2023). "However, ubiquitous expression of BCL-2 family proteins limits the clinical application of certain BH3 mimetics, as some non-cancer cells are intrinsically dependent on BCL-XL or MCL-1." (PMID 37898609, 2023). "MCL-1 overexpression is common in various cancer types, including BC." (PMID 37885779, 2023). "As a CAP-dependent transcript, MCL1 expression may also be influenced via translational regulation, which could contribute to higher MCL1 expression in chemoresistant cancer." (PMID 37723317, 2023). "Notably, introducing double-point mutations in lysines 404/412 of FBW7 to arginine which makes it resistant to proteasomal degradation, leads to the sharp reduction of MCL-1 protein levels and sensitizes cancer cells to Taxol-induced cell death." (PMID 36672454, 2023). "Splicing dysregulation of MCL-1 may lead to resistance toward apoptosis and is observed in various types of cancers." (PMID 37108344, 2023). "In addition to CCND1, several other cancer-relevant genes, including MCL1, BCL2L1, CDC25, FAS, and HIF1A, were among the common genes." (PMID 36807142, 2023). "However, in cancer cells, MCL1 expression is often up-regulated, leading to increased cell survival and resistance to chemotherapy drugs." (PMID 37744271, 2023). "Mcl-1 expression is elevated during chemotherapy and may be involved in cancer treatment resistance." (PMID 37896184, 2023). "This leads to the effect in which the upregulation of MCL1 in these cancers not only suppresses the traditional Bcl-2 family regulation of apoptosis, but also suppresses the specific upregulation of TP73 and the resulting anti-tumor effects of these platinum-based compounds." (PMID 37760451, 2023).
cancer (continued). "In addition, gossypol, a natural phenolic compound found in cotton plants, has been depicted as inhibiting Bcl-2, Bcl-xL, Bcl-W, and Mcl-1 in various cancers, including prostate cancer, breast cancer, leukemia, and gliobastoma." (PMID 36982637, 2023). "The balance between MCL-1 and NOXA may determine the susceptibility of cancer cells to drug-induced apoptosis, and the degradation of NOXA/MCL-1 complexes has been shown as determining the response of cancer cells to antimitotic treatment." (PMID 37835493, 2023). "Our data show remarkable downregulation of MCL-1 protein and near complete reversal of Taxol resistance by overexpression of highly stabilized FBW7 2R-mutant which demonstrates the power of mitigating FBW7 and MCL-1 protein levels in human cancers for efficient chemotherapy response." (PMID 36672454, 2023). "These events were not a consequence of cell death, as BAX/BAK-deficient cancer cells exhibited similar downregulation of mTORC1 activity and MCL-1-protein levels." (PMID 37684238, 2023). "Similar to BCL-2, MCL-1 is highly expressed in a range of cancer cells." (PMID 37864894, 2023). "Overexpression of the Mcl-1 protein or amplification of the Mcl-1 gene in malignant cells can prevent apoptosis and reduce sensitivity to commonly used anticancer drugs, making Mcl-1 a potential drug target for cancer." (PMID 37259388, 2023). "In particular, MCL-1 inhibition may lead to BCL-XL overexpression in cancer cells as a compensatory survival adaptation." (PMID 37108344, 2023). "Therefore, there is significant interest in developing drugs that can inhibit MCL1 expression or function as a potential cancer treatment strategy." (PMID 37744271, 2023). "MCL-1 upregulation may also play a significant role in cancer cell survival and drug resistance in ACC with MYB overexpression." (PMID 37511133, 2023). "Mcl-1 protein is often overexpressed in various cancers and is necessary for AML survival." (PMID 37599786, 2023). "Both MCL1 and Bcl-XL are antiapoptotic genes and contribute to the radioresistance in cancer cells." (PMID 38062011, 2023). "Of the six antiapoptotic Bcl-2 family proteins, Bcl-B, Bfl-1, and Mcl-1 are more prone to basal or drug-mediated proteasomal turnover in cancer cells; this turnover could limit their functional activity." (PMID 37899453, 2023). "As an important pro-survival protein, Mcl-1 is over-expressed in various types of cancer." (PMID 36658493, 2023). "However, venetoclax resistance in cancer cells has already emerged due to acquired mutations in BCL-2 and upregulation of BCL-XL or MCL-1." (PMID 37684238, 2023). "BC cells may rely on MCL-1 for survival in preclinical models, and inhibiting MCL-1 can improve the efficacy ofconventional cancer treatments." (PMID 37885779, 2023). "This does not affect MAPK as is generally thought, however, MAPK and PI3K pathways jointly regulate Mcl-1 which is an anti-apoptotic factor that may promote cancer cell survival and growth." (PMID 37231247, 2023). "Therefore, the overexpression of the MCL1 gene product exhibited by cancer cells results in resistance to anticancer therapies." (PMID 37686541, 2023). "However, venetoclax selectively binds to Bcl-2 and has limited efficacy against cancer cells that depends on other anti-apoptotic proteins for survival such as Mcl-1." (PMID 36658493, 2023). "Consequently, our findings uncover PFKFB3 inhibition as an Ca2+-independent mechanism through which BAPTAi impairs cellular metabolism and ultimately compromises the survival of MCL-1-dependent cancer cells." (PMID 37684238, 2023). "This may be mediated by gene amplification of MCL1 in subpopulations of cancer cells that encounter a survival benefit during chemotherapy." (PMID 37723317, 2023). "However, YM155 also inhibits Mcl-1 expression in prostate cancer PC-3, mesothelioma H28, glioblastoma U251, and D37 cancer cells." (PMID 36771042, 2023).
cancer (continued). "Moreover, Mcl-1 dependent cancers are resistant to pan Bcl-2/Bcl-xL inhibitors (ABT-737), and venetoclax." (PMID 36986514, 2023). "This tight regulation of Mcl-1 expression is altered significantly in several cancers." (PMID 37736508, 2023). "Mcl-1 plays a key role in the survival and development of cancer cells." (PMID 37259388, 2023). "This makes MCL1 an attractive target for cancer therapy development." (PMID 37744271, 2023). "Therefore, one of the pathways associated with apoptosis factors attended to be targeted for cancer therapy is the anti-apoptotic B-cell lymphoma-2 (Bcl-2) family of proteins, including Bcl-w and Bcl-xL Bfl1/A-1, Bcl-2, Mcl-1, and Bcl-B." (PMID 36820406, 2023). "This metabolic action of Mcl-1 during periods of stress may provide additional support to cancer cells that extend beyond survival." (PMID 37521407, 2023). "Mcl-1 was observed to be getting increased in a different range of cancers." (PMID 37736508, 2023). "Moreover, MCL1 protein was involved in intrinsic drug resistance in cancer therapy, such as poor response to paclitaxel treatment in a cohort of invasive BC patients which showed increased MCL1 protein levels after treatment." (PMID 37446326, 2023). "As for Mcl-1, its oncogenic activities have drawn particular attention in recent years, due to frequent amplifications of the Mcl-1 gene in about 40% of cancer cells of different origin, and due to an often high Mcl-1 expression, which was correlated to tumor progression and drug resistance." (PMID 36902392, 2023). "In human cancer cells, the downregulation of pro-apoptotic proteins (e.g. Bax, Bak, Bad, Bim) and the upregulation of anti-apoptotic proteins (e.g. BCL-2, BCL-xl, MCL-1), inhibits the release of cytochrome c from mitochondria, leads to the immortal character of the cancer cells." (PMID 37730790, 2023). "MCL1 is one of the most frequently dysregulated apoptotic genes in cancers." (PMID 36329234, 2023). "MCL-1 inhibits chemotherapy induced senescence, thus mediating resistance to cancer therapy." (PMID 37601693, 2023). "As a result, MCL-1 has become a promising target for cancer therapy." (PMID 37481672, 2023). "Constitutive activation can be found in several types of human cancer, and it is able to increase the level of different cancer-related molecules, such as surviving, Bcl-XL, cyclin D1/D2, C-Myc, Mcl-1, and vascular endothelial growth factor (VEGF), favoring tumorigenic progression." (PMID 35890348, 2022). "Targeting Mcl-1 appears to be a promising strategy in cancer therapy." (PMID 35301297, 2022). "Furthermore, ATF5 promotes cancer cell survival by inducing the transcription of the pro-apoptotic gene Mcl-1." (PMID 35328718, 2022). "As Mcl-1 is a promising target in cancer treatment, there is much hope that Mcl-1-based strategies may also be well tolerated." (PMID 36293331, 2022). "Interestingly, we find that the Myeloid Cell Leukemia 1 (Mcl-1) is the most expressed anti-apoptotic gene in senescent tumor cells, being overexpressed even in Bcl-2-negative senescent cancer cells." (PMID 35449130, 2022). "Mcl-1 was recognized among the top molecule in cancers for somatic copy number alterations." (PMID 35273915, 2022). "Recent studies have also revealed that MCL1 is a therapeutic prospective target in cancers." (PMID 35769708, 2022). "Mcl-1 overexpression has been associated with poor prognosis in a wide variety of cancers irrespective of their lineages." (PMID 36045907, 2022). "Thus, genetic ablation of MCL1 makes cancer cells sensitive to the targeting of non-MCL1 Bcl-2 family members such as Bcl-xL in CRC." (PMID 35042842, 2022). "Except MCL-1, c-Myc is also an oncogene and is highly expressed in many cancers." (PMID 36188217, 2022).